METTL3 (methyltransferase 3, N6-adenosine-methyltransferase complex catalytic subunit)
Diseases named in the same sentence as METTL3 in open-access papers (continued):
Sharing a sentence is not in itself a finding about the gene and the disease.
colorectal cancer (continued). "In colorectal cancer, the reduction of METTL3 or METTL14 rises cytotoxic tumor-infiltrating CD8+ T cells and stimulates the recruitment of CD4+ and CD8+ effector T cells that suppress tumor growth." (PMID 37236993, 2023). "In colorectal cancer, METTL3 cooperates with IGF2BP2 to increase the stability of SOX2 RNA, which promotes the transcription of MYC and enhances the self-renewal and proliferation of tumor cells." (PMID 37996892, 2023). "Research indicates that METTL3 plays a crucial role in advancing MDSC migration in colorectal cancer by exerting control over the m6A-BHLHE41-CXCL1/CXCR2 axis." (PMID 38187373, 2023). "In the latest literature published in 2023, breast cancer and colorectal cancer accounted for a significant proportion of publications, illustrating that these diseases were still the main research areas where METTL3 plays a regulatory role." (PMID 36970605, 2023). "This study revealed the upregulation of METTL3 expression and m6A level in colorectal cancer compared with normal tissues." (PMID 38001065, 2023). "Some studies have also proved that the up-regulation of METTL3 is one of the reasons for the abnormal modification of m6A in colorectal cancer, and it is positively correlated with tumor metastasis." (PMID 37936074, 2023). "In colorectal cancer, Peng showed that METTL3 affects the ERK pathway by regulating the miR-1246/SPRED2 signaling axis and enhancing the invasion ability of cancer." (PMID 37095108, 2023). "In colorectal cancer cells, METTL3 directly acts on HK2 and GLUT1 mRNA, and the stability of HK2 and GLUT1 mRNA modified by m6A increases." (PMID 37582735, 2023). "METTL3 was confirmed to form m6A in flanking reverse complementary sequences of circ1662, remarkably elevating the expression of circ1662 in colorectal cancer." (PMID 36875073, 2023). "While preserving the activation and proliferation of CD4+ and CD8+ T cells and preventing the growth of colorectal tumors, METTL3 knockdown in colorectal cancer cells reduces myeloid-derived suppressor cell (MDSC) infiltration." (PMID 37020540, 2023). "In colorectal cancer, METTL3 stabilizes HK2 and GLUT1 to activate aerobic glycolysis pathway via the deposited m6A in the 3’UTR/5’UTR." (PMID 37996892, 2023). "Here, we revealed that upregulated methyltransferase-like 3 (METTL3) in colorectal cancer exerted both methyltransferase activity-dependent and -independent functions in gene regulation." (PMID 38001065, 2023). "In colorectal cancer, circQSOX1 is methylated under the action of METTL3, and its stability is improved after binding with IGF2BP2." (PMID 37582735, 2023). "Overexpression of METTL3 drove glycolytic metabolism in colorectal cancer through increasing glucose uptake, lactic acid production and ATP level." (PMID 37626036, 2023). "In colorectal cancer, H3K4me3 is enriched in the METTL3 promoter region and promotes METTL3 expression through methylation." (PMID 37996892, 2023). "In summary, our work has demonstrated that METTL3 promoted colorectal cancer progression through upregulating JAK1 and STAT3 expression in m6A-dependent and -independent manners, contributing to the activation of the p-STAT3 signaling pathway." (PMID 38001065, 2023). "In colorectal cancer, expression of the non-coding RNA circ1662 is upregulated by METTL3-mediated m6A modification." (PMID 37996892, 2023). "High expression of METTL3 has been shown to be highly expressed in colorectal cancer and correlated with low OS in patients." (PMID 37781524, 2023). "In colorectal cancer, METTL3 regulates long chain noncoding RNA HNF1A-AS1 expression, accelerating cell cycle progression and promoting proliferation." (PMID 37996892, 2023). "METTL3 is significantly upregulated in colorectal cancer tissues, and promotes its malignancy via stabilizing Snail mRNA." (PMID 35217651, 2022).
colorectal cancer (continued). "On the other hand, METTL3 stabilizes its expression level by methylating the m6A site of the CCNE1 3′UTR mRNA to increase the expression of the cyclin E1 to promote colorectal cancer cell proliferation." (PMID 35614935, 2022). "In human colorectal cancer, up-regulation of METTL3 can promote the metastasis of colorectal cancer cells via the miR-1246/SPRED2/MAPK pathway." (PMID 35794583, 2022). "METTL3 regulates the expression of various oncogenes and tumor suppressor genes at the post-transcriptional level to enhance the progression of colorectal cancer." (PMID 35614935, 2022). "In colorectal cancer, Sec62 is activated by METTL3-mediated m6A modification, which enhances Wnt signaling by binding to β-catenin, thereby affecting the prognosis of colorectal cancer." (PMID 35774359, 2022). "For example, METTL3 promotes colorectal cancer by activating the m6A-GLUT1-mTORC1 axis; YTHDF2 mediates lipopolysaccharide-induced osteoclastogenesis and inflammatory response via the NF-κB and MAPK signaling pathways." (PMID 35794625, 2022). "YPEL5 was found to be inhibited by METTL3-m6A (N6-methyladenosine)-YTHDF2 axis in colorectal cancer, promoting the growth and metastasis of tumor." (PMID 35265613, 2022). "METTL3 is upregulated in most tumors, including nasopharyngeal, gastric, liver cancer and bladder cancer, but it is downregulated in colorectal cancer." (PMID 35742899, 2022). "In contrast, in colorectal cancer cells, Mettl3 over-expression resulted in decreased migration, while decreased Mettl3 activated the p38/ERK pathways, resulting in increased migration." (PMID 35350378, 2022). "METTL3 also regulates the progression of colorectal cancer by affecting the metabolism of tumor cells." (PMID 35614935, 2022). "As an important member of m6A methylation regulators, METTL3 is upregulated in osteosarcoma, melanoma, liver cancer, and colorectal cancer." (PMID 36463205, 2022). "The accumulation of myeloid-derived suppressor cells necessary to maintain the activation and proliferation of CD4+ and CD8+ T cells was reduced when METTL3 was selectively depleted in colorectal cancer cells." (PMID 36591468, 2022). "Through the regulation of the m6A-GLUT1-mTORC1 axis, METTL3 is actively involved in the proliferation of colorectal cancer, and simultaneous inhibition of mTORC1 and METTL3 has an additive effect on the treatment of colorectal cancer." (PMID 35614935, 2022). "In colorectal cancer, METTL3 promotes glycolysis metabolism to drive tumorigenesis, mechanistically, METTL3 mediates m6A modification to enhance the expressions of HK2 and SLC2A1 through IGF2BP2/3-dependent mRNA stability function." (PMID 35541906, 2022). "Mechanistically, exosomal circLPAR1 expression level led to decreased BRD4 levels because it binds eIF3h and inhibits the METTL3–eIF3h interaction, which remarkably suppressed colorectal cancer development." (PMID 35164758, 2022). "METTL3-induced lncRNA RP11 has been shown to trigger the dissemination of cells via post-translational upregulation of Zeb1 in colorectal cancer." (PMID 35941582, 2022). "The latest findings have confirmed that METTL3 hampered colorectal cancer cell necroptosis to promote oxaliplatin resistance." (PMID 35090469, 2022). "It was found that METTL3 expression was increased in tumor tissues of colorectal cancer patients, and the higher its expression, the worse the prognosis of patients." (PMID 35614935, 2022). "Through a m6A-IGF2BP2-dependent pathway in colorectal cancer cells, METTL3 knockdown significantly decreased in vitro cell self-renewal, frequency of the stem cell population, and migration, as well as colorectal carcinoma tumorigenesis and metastasis." (PMID 35860262, 2022). "In colorectal cancer, METTL3 facilitated tumor metastasis by m6A-mediated methylation to enhance PLAU stability." (PMID 36476503, 2022).
colorectal cancer (continued). "In colorectal cancer, METTL3 expression was found to be much higher in patients with higher FDG uptake, promoting cancer progression, which depends on cell glycolytic metabolism, by stabilizing HK2 and GLUT1 expression in an m6A-IGF2BP2/3-dependent manner." (PMID 34996469, 2022). "Another study revealed that METTL3 level was elevated in colorectal cancer metastatic tissues and it was predictive of poor prognosis." (PMID 35280730, 2022). "Mechanistically, exosomal circLPAR1 is internalized by colorectal cancer cells and binds eIF3h to reduce METTL3-eIF3h-dependent mRNA translation, thereby inhibiting BRD4 expression and suppressing cellular proliferation, invasion, and migration." (PMID 35164758, 2022). "Previous studies have shown that the m6A-modified genes perform a carcinogenic role in some instances, such as in colorectal cancer where the overexpression of METTL3 leads to higher m6A levels of the oncogene SOX224." (PMID 35075167, 2022). "Previous researchers investigated the mechanisms underlying resistance to oxaliplatin in colorectal cancer and found that the mRNA and protein levels of TRAF5 increased when METTL3 was knocked out; the overexpression of METTL3 had the opposite result." (PMID 35141221, 2022). "In colorectal cancer, METTL3 promoted GLUT1 translation in an m6A-dependent manner, which resulted in downstream activation of mTORC1 and increased cell survival and proliferation." (PMID 35350378, 2022). "In colorectal cancer, nasopharyngeal carcinoma, and hepatocellular carcinoma, METTL3 methylates Snail mRNA, thereby stabilising it and promoting tumour deterioration." (PMID 36358640, 2022). "For instance, colorectal cancer metastatic tissues with increased METTL3 expression were related with a worse prognosis." (PMID 35860262, 2022). "RNA N6-methyladenosine methyltransferase METTL3 facilitates colorectal cancer by activating the m6A–GLUT1–mTORC1 axis." (PMID 35681299, 2022). "For example, in colorectal cancer, forkhead box D3 acts as a transcription factor of METTL3 and inhibits colorectal cancer metastasis by promoting METTL3 expression." (PMID 36424383, 2022). "The latest study ascertained that reduced m6A modification by knocking out methyltransferase genes, Mettl3 and Mettl14, enhanced response to PD-1 inhibitors in murine colorectal carcinoma cell line CT26." (PMID 35382776, 2022). "In colorectal cancer, METTL3 induces m6A methylation of lncRNA LBX2-AS1 mRNA, thereby improving its mRNA stability and ultimately promoting its expression." (PMID 35070987, 2021). "Elevated METTL3 level with subsequent downregulation of SOCS2 was also observed in colorectal cancer (CRC)." (PMID 33814008, 2021). "Since METTL3 plays overlapping roles in tumors, its high expression was shown to be positively correlated with better survival in colorectal cancer." (PMID 34616742, 2021). "In colorectal cancer, METTL3 promotes tumor metastasis, stemness, and chemoresistance through activation of MAPK and Wnt/β-catenin signaling." (PMID 34616742, 2021). "In colorectal cancer, METTL3 acts as a tumor suppressor on cell proliferation, migration, and invasion via the p38/ERK pathway." (PMID 33490266, 2021). "For instance, inhibition of METTL14 promotes the proliferation and invasion of GC cells by activating Wnt pathway, downregulation of METTL3 promotes metastasis of colorectal cancer cells through MAPK pathway." (PMID 34702266, 2021). "METTL3 is upregulated in most tumors, including nasopharyngeal, gastric, liver, and bladder cancers, but it is downregulated in colorectal cancer." (PMID 34858499, 2021). "Here, we demonstrate that methyltransferase‐like 3 (METTL3)‐catalyzed N6‐methyladenosine (m6A) modification facilitates tumor growth and metastasis in colorectal cancer (CRC)." (PMID 33411363, 2021). "For example, loss of METTL3 and METTL14 expression increases the response to anti-PD-1 treatment in colorectal cancer with low mutational burden." (PMID 34616742, 2021).
colorectal cancer (continued). "For example, methyltransferase-like 3 (METTL3), the first methylase to be identified, was dysregulated in multiple malignant tumor types, including colorectal cancer, bladder cancer, lung cancer, and melanoma." (PMID 35096816, 2021). "METTL3 is an effective therapeutic target for various cancers, including pancreatic cancer, melanoma, colorectal cancer, and lung adenocarcinoma." (PMID 34336690, 2021). "More importantly, it was reported that METTL3 can promote colorectal cancer metastasis through methylating pri-miR-1246 and accelerating its maturation." (PMID 34497267, 2021). "For instance, METTL3 facilitated the tumorigenesis and metastasis of colorectal cancer by inhibiting YPEL5 expression in a YTHDF2 (an m6A reader)-dependent manner." (PMID 34950654, 2021). "In colorectal cancer and melanoma, simultaneous depletion of METTL3 and METTL14 induces mass production of cytokines, including IFN‐γ, CXCL9, and CXCL10." (PMID 34586737, 2021). "For instance, METTL3 was found to be upregulated in colorectal cancer (CRC), and high METTL3 expression was associated with poor OS in CRC patients." (PMID 33816266, 2021). "METTL3 regulates colorectal cancer metastasis by enhancing the mRNA stability of SOX2, HK2 and SLC2A1 (GLUT1) through an m6A-IGF2BP2/3-dependent mechanism." (PMID 34094960, 2021). "Previous research has suggested that METTL3 is an oncogene in different cancers, like colorectal carcinoma, bladder cancer, and pancreatic cancer 27-29." (PMID 33976730, 2021). "In colorectal carcinoma, in particular, METTL3 can facilitate carcinogenesis via an IGF2BP2-dependent process that inhibits SOX2 degradation." (PMID 34105069, 2021). "METTL3 acts as an oncogene in colorectal cancer via its interaction with the glycolysis components, hexokinase 2 (HK2) and glucose transporter 1 (GLUT1) mRNAs, in an m6A-dependent manner." (PMID 32709063, 2020). "RNA methyltransferase METTL3 has been found to facilitate colorectal cancer by activating m6A-GLUT1-mTORC1 axis and is a therapeutic target." (PMID 33575259, 2020). "To investigate the potential role of m6A in colorectal cancer, we first detected the mRNA levels of major m6A methyltransferase including METTL3 and METTL14 in 37 CRC and paired normal samples." (PMID 32111213, 2020). "Deng et al51 observed that high expression of METTL3 was strongly correlated with better prognosis, indicating its tumour‐suppressive role in colorectal cancer." (PMID 32615646, 2020). "Knockdown of METTL3 suppresses the self-renewal, stem cell frequency and migration of colorectal cancer cells in vitro, and inhibits the colorectal tumor growth and metastasis in vivo." (PMID 33372610, 2020). "As the critical N6‐methyladenosine (m6A) methyltransferase, the roles of methyltransferase like 3 (METTL3) in colorectal cancer (CRC) are controversial." (PMID 32039568, 2020). "A study in colorectal carcinoma showed that higher expression of METTL3 promotes m6A levels in SOX2 transcripts." (PMID 33228740, 2020). "METTL3 has been reported as a potential biomarker panel for prognostic prediction in colorectal carcinoma." (PMID 32211315, 2020). "Among these genes, SOX2 exhibited the most consistently decreased m6A level in METTL3-knockdown colorectal cancer cells compared with control cells." (PMID 31921660, 2019). "Knockdown of METTL3 in colorectal cancer cells significantly inhibited tumorigenesis and metastasis, cell self-renewal, and the frequency and migration of stem cells in vitro and in vivo, suggesting the oncogenic role of METTL3 in colorectal cancer." (PMID 31921660, 2019). "Li and her colleagues found that after knockdown of METTL3 in colorectal cancer cells, the genes with the greatest expression changes were enriched in the stem cell differentiation pathway." (PMID 31921660, 2019).
colorectal cancer (continued). "METTL3 expression was consistently elevated in recurrent colorectal cancer, matched lymph node, and metastatic liver tissues." (PMID 31921660, 2019). "Similarly, in colorectal cancer, Mettl3 drives tumor progression by sustaining HDGF expression and promoting glycolysis." (PMID 41517663, 2026). "Thus, Mettl3 has been identified as a promoter of colorectal cancer through the activation of the m6A-GLUT1-mTORC1 axis." (PMID 41517663, 2026). "Mettl3’s involvement in this pathway leads to the suppression of key signaling molecules, thereby impeding cell proliferation, migration, and the overall progression of colorectal cancer." (PMID 41517663, 2026). "Inhibition of mTORC1 signaling may potentiate the anticancer effects of Mettl3-mediated silencing in colorectal cancer." (PMID 41517663, 2026). "Strikingly, m6A modification regulates both tumor-intrinsic and immune cell functions: METTL3-mediated m6A deposition in colorectal cancer suppresses CD8+ T-cell infiltration, while METTL3 inhibition synergizes with anti-PD-1 therapy to enhance tumor clearance." (PMID 40130175, 2025). "Moreover, METTL3 mediates the expression of REG1α in an m6A dependent manner to activate glycolysis process of colorectal cancer cells." (PMID 40097750, 2025). "For instance, the m6A writer METTL3 can suppress cytotoxic T-cell infiltration in colorectal cancer by destabilizing the CXCL1 and IL-8 transcripts, whereas the eraser ALKBH5 promotes PD-L1 degradation in melanoma through YTHDF2-mediated transcript destabilization." (PMID 40867324, 2025). "The lncRNA 00460/IGF2BP2 complex May promote colorectal cancer cell proliferation by mediating high mobility group AT-hook 1 (HMGA1) transcript stability through METTL3-dependent m6A modification." (PMID 40986143, 2025). "Besides, H3K18 lactylation is enriched in the tumor microenvironment, which upregulates METTL3 to facilitate tumor growth in colorectal cancer." (PMID 39217289, 2024). "Moreover, in colorectal cancer, METTL3 targets genes such as SOX2, HK2, SLC2A1, and CBX8, inducing metastasis-related processes and activating the glycolysis pathway and cellular stemness." (PMID 38966069, 2024). "SLC2A1′s involvement in METTL3-mediated glycolysis has been observed in colorectal cancer." (PMID 39593730, 2024). "Additionally, colorectal cancer cells expressing METTL3 recruit M2-type macrophages by secreting CXCL2." (PMID 38605400, 2024). "Interestingly, METTL3 exhibited its cancer suppressive effects in CRC by regulating the p38/ERK pathway, which suggests us that METTL3 plays a rather complex role in the regulation of colorectal cancer." (PMID 39289775, 2024). "Similarly, elevated METTL3 suppresses colorectal cancer proliferation and migration, while METTL3 promotes colorectal cancer tumorigenesis and metastasis." (PMID 39103890, 2024). "Furthermore, METTL3 exerts a significant influence on the progression of colorectal cancer through glycose metabolism via an m6A-IGF2BP3-dependent mechanism." (PMID 38902779, 2024). "METTL3-mediated m6A modification stabilized circQSOX1 in colorectal cancer." (PMID 38641828, 2024). "Moreover, colorectal cancer cells expressing METTL3 recruit M2 macrophages by secreting CXCL2, a finding confirmed through in vitro experiments and in vivo experiments with METTL3-silenced colorectal cancer cells." (PMID 38605400, 2024). "While the manuscript was being prepared, a number of research revealed that METTL3 may control PD-L1 expression or be involved in immunotherapy for lung cancer and colorectal cancer, implying the complicated role of METTL3 in carcinogenesis." (PMID 38012755, 2023). "In summary, optimizing the response of CRC patients to ICIs by directly targeting METTL3/14 or its downstream mechanisms may be a new avenue for developing future immunotherapy of colorectal cancer." (PMID 38187373, 2023). "In addition, METTL3-mediated m6A modifications were translated into pro-tumorigenic signals in colorectal cancer." (PMID 37344779, 2023).